HPSE (heparanase)
Diseases named in the same sentence as HPSE in open-access papers (continued):
Sharing a sentence is not in itself a finding about the gene and the disease.
tumor (continued). "Herein, Salmonella reduced the function and expression of heparanase, a major enzyme involved in tumor metastasis, in tumor cells via the AKT/ERK signaling pathway." (PMID 34220326, 2021). "It has been reported that the expression of growth factors such as VEGF, HGF, bFGF, FGF-2, and transforming growth factor-β/β1 which play essential roles in EMT, bone formation, angiogenesis, tumor angiogenesis, and renal diseases, are regulated by heparanase." (PMID 34681753, 2021). "Heparanase not only enhances tumor metastasis but is also involved in the regulation of multiple proteins that promote the aggressive biological behavior of tumor, including VEGF and MMP-9 3-6." (PMID 34220326, 2021). "Compelling evidence ties heparanase, an endoglycosidase that cleaves heparan sulfate side (HS) chains of proteoglycans, with all steps of tumor development, including tumor initiation, angiogenesis, growth, metastasis, and chemoresistance." (PMID 34199150, 2021). "HS mimetics are an emerging class of antitumor drugs characterized by a complex mechanism of action based on interference with both heparanase and HSPGs’ functions, thereby potentially affecting tumor deregulated and microenvironment-dependent pathways." (PMID 34857011, 2021). "Overweight IBrC subjects and those with a tumour diameter of ≥2 cm demonstrated a lower chance of a lower pre-treatment heparanase concentration." (PMID 34070058, 2021). "Since cellular plasticity is a major contributor to tumor progression and therapy failure, and our enriched analysis identified that HPSE-high is associated with regulators of differentiation we evaluated whether high HPSE expression is associated with distinguishable differentiation states." (PMID 34050190, 2021). "The expression of HPSE is not only confined to tumour cells, but to other cell types in the TME as well." (PMID 33256730, 2020). "Adding to this complexity are the recent findings that HPSE plays a role in preventing tumours through activating cells of the innate immune system." (PMID 33256730, 2020). "For heparin, various different mechanisms have been identified which interfere with the metastatic spread of tumor cells such as inhibition of adhesion receptors or enzymes such as heparanase." (PMID 32110917, 2020). "HPSE release can therefore be a strategy used by metastatic tumor cells to invade blood and lymphatic vessels." (PMID 31963505, 2020). "Targeting of heparanase in the tumor microenvironment is a promising strategy to restrain tumor growth and dissemination." (PMID 31963505, 2020). "Type I hypercoagulability results from the degradation of endogenous heparin by tumor-secreted heparanase." (PMID 32121387, 2020). "This study provided evidences that hinokitiol can inhibit heparanase expression via protein kinase B (Akt) and extracellular signal-regulated kinase (Erk) signaling pathways, leading to a reduction in tumor metastasis." (PMID 32132875, 2020). "Together, these data indicate that heparanase reduces levels of nuclear PTEN thereby reducing its tumor suppressive function in these cells as manifested by upregulation of genes that drive tumor growth and progression." (PMID 32899927, 2020). "Based on the findings, it can be assumed that Akt is located upstream of Erk in 4T1 tumor cell line, indicating that Akt affect Erk phosphorylation and then downregulate heparanase expression after treatment with hinokitiol." (PMID 32132875, 2020). "The relationship between HPSE expression, lymphangiogenesis and overall tumour grade has been demonstrated in a number of studies." (PMID 33256730, 2020). "Restored baseline IFP and vessel function is of major importance for successful CAR T cell delivery to the tumor, even if they are provided with infiltration-increasing mechanisms, such as heparanase." (PMID 32481570, 2020).
tumor (continued). "Impact of heparanase on tumor progression is related to its function in mediating tumor-host cross-talk, priming the tumor microenvironment to better support tumor seeding and growth." (PMID 31963505, 2020). "The significant increase in the SP as a result of HPSE overexpression provides further evidence for the multifunctional roles of HPSE in the tumor microenvironment." (PMID 32477959, 2020). "We will initially review the classical mechanism of cancer-associated thrombosis (type II), and then we will focus on the role of degradation of endogenous heparin by tumor-secreted heparanase (type I)." (PMID 32121387, 2020). "Since hinokitiol inhibited heparanase expression, we predicted that hinokitiol can reduce tumor cell migration." (PMID 32132875, 2020). "Splice 36 of Spalax heparanase functions as a dominant negative to the wild-type enzyme and inhabits heparan sulphate degradation, tumor growth, and metastasis in animal models." (PMID 32121387, 2020). "HPSE expression was shown to reduce mTOR1 activity, which promoted autophagy, thus enhancing tumour growth and chemoresistance." (PMID 33256730, 2020). "The interaction of enoxaparin sodium with heparanase at the start of the tumor metastasis process would appear to be closely related to the phenomenon of reduction in cell migration." (PMID 33312942, 2020). "The overexpression of HPSE in cancer thus enhances tumour growth and metastasis, resulting in a poor clinical prognosis." (PMID 33256730, 2020). "The overexpression of HPSE in mouse organs and human tumours has been shown to correlate with enhanced 6-O-sulphation of HS, which promoted the formation of ternary complexes with FGF-1 or -2 and FGFR." (PMID 33256730, 2020). "HPSE functions inside the cell to promote autophagy and tumor growth by driving fusion of lysosomes with autophagosomes thus controlling the basal levels of autophagy." (PMID 31963505, 2020). "Essentially, all cancers examined to date have been reported to overexpress heparanase, leading to enhanced tumour growth and metastasis with concomitant poor patient survival." (PMID 33256730, 2020). "This treatment inhibits the tumor Heparanase enzyme, which promotes extracellular matrix degradation and tumor invasion/metastases." (PMID 32153582, 2020). "Hinokitiol can effectively downregulate tumor-induced heparanase expression in B16F10 and 4T1 cancer cell lines through the suppression of Akt and Erk signaling pathways." (PMID 32132875, 2020). "Numerous studies using pre-clinical disease models and patient tumour samples have demonstrated the key role of HPSE in activating the angiogenic switch and promoting this hallmark, as highlighted below." (PMID 33256730, 2020). "Type I occurs when the balance of endogenous heparin production and degradation is disturbed, with increased degradation of endogenous heparin by tumor-secreted heparanase." (PMID 32121387, 2020). "For instance, heparin efficiently blocks enzymes such as heparanase or matrix metalloproteinases, binds growth factors and chemokines, blocks various adhesion receptors, and can sensitize tumor cells for cytotoxic drugs among many other mechanisms." (PMID 32110917, 2020). "Through all these mechanisms, HPSE2 inhibits heparanase and thus lessens its tumor-promoting actions." (PMID 32175269, 2020). "Regarding the use of heparanase inhibitors to block tumor progression and their weak anticoagulant activity, Muparfostat PI-88 was the first heparanase inhibitor tested in early stage clinical trials in cancer patients in 2011." (PMID 31963505, 2020). "A number of clinical studies have demonstrated that the expression of HPSE at the tumour invasion front leads to a poor patient prognosis." (PMID 33256730, 2020). "HPSE2 also promotes tumor suppression by downregulating the transcription factor Id1, further inhibiting heparanase activity and stimulating endoplasmic reticulum stress." (PMID 32175269, 2020).
tumor (continued). "Cancer cells can release a large amount of heparanase, which degrades the basement membrane of blood vessels and the extracellular matrix, thus promoting invasion and metastasis of tumor cells." (PMID 32175269, 2020). "From the results above, we now know that either the addition of resveratrol or Akt transfection in tumor cells enhanced phospho-Erk and phospho-Akt and increase heparanase expression after that." (PMID 32132875, 2020). "Heparanase activation expedites the movement of tumor cells through the ECM and BM, facilitating metastasis." (PMID 32471161, 2020). "In vivo studies using heparanase inhibitors in animal tumor models have also demonstrated reductions in tumor metastasis." (PMID 32471161, 2020). "Numerous clinical association studies have consistently demonstrated that upregulation of heparanase expression correlates with increased tumor size, tumor angiogenesis, enhanced metastasis, and poor prognosis." (PMID 31963505, 2020). "PAR-1 activation with TRAP-6 induced a more pronounced heparanase release than platelet activation by the two tumor cell lines." (PMID 32110917, 2020). "The dual role of heparanase within the tumour microenvironment, however, emphasises the need for further investigation into defining its precise mechanism of action in different cancer settings." (PMID 33256730, 2020). "Patients with hepatitis-C-related hepatocellular carcinoma showed a higher level of HPSE expression, which correlated with tumour angiogenesis and invasion." (PMID 33256730, 2020). "Subsequently, we treated the Akt transfected-tumor cells with hinokitiol to examine the changes in heparanase expression and Akt phosphorylation." (PMID 32132875, 2020). "In other cancer types, heparanase activation has been indicated in promoting metastasis and tumor progression." (PMID 32471161, 2020). "Together these findings indicate that nuclear heparanase plays an important role in tumor progression by promoting chromatin remodeling that opens its conformation allowing access to promotors of genes that drive progression." (PMID 32899927, 2020). "Increased heparanase expression is also often described to promote an aggressive tumor behavior via multiple mechanisms." (PMID 31963505, 2020). "HPSE continues to generate significant interest as a potential therapeutic target due to its multiple roles in tumour progression." (PMID 33256730, 2020). "For example, a significant tumor cell growth reduction in vitro and prolonged survival in vivo were reported upon treatment with a HS-mimetic heparanase inhibitor PG545." (PMID 33330449, 2020). "In contrast, knockdown of heparanase or treatments of tumor-bearing mice with heparanase-inhibiting compounds markedly attenuate tumor progression, further underscoring the potential of anti-heparanase therapy for multiple types of cancer." (PMID 31963505, 2020). "Evasion genes of the immune system co-expressed with heparanase-1, a enzyme related with tumor progression." (PMID 33053017, 2020). "This review will explore the myriad ways by which heparanase functions as a key regulator of the hallmarks of cancer and will highlight its role as a major component within the tumour microenvironment." (PMID 33256730, 2020). "These signatures were consistent with the known function of heparanase in driving tumor progression." (PMID 32899927, 2020). "The release of heparanase from tumor cells into the ECM promotes cleavage of HS fragments, which in turn liberates bound growth factors that act to further support tumor angiogenesis." (PMID 32010611, 2019). "Heparanase is primarily known for its role in tumour progression, but recent information has revealed other roles including in fibrosis, autophagy and inflammation." (PMID 30845788, 2019). "Since heparanase is known to be involved in tumor progression, several inhibitors of this enzyme have been produced as novel cancer therapeutics." (PMID 30922347, 2019).
tumor (continued). "We were interested in investigating the mechanism of interaction between tumor cells and lymphocytes that activates heparanase expression in malignant neoplasms." (PMID 30922347, 2019). "Over-expression of heparanase (HPSE), an enzyme that cleaves HS chains of HSPGs at β-1,4 positions, has been shown to be involved in mechanisms promoting tumor growth, angiogenesis, and metastasis." (PMID 31013618, 2019). "We are just beginning to understand the influence of heparanase on a pro/anti-tumor immune response, and there are still many questions to answer." (PMID 31110966, 2019). "Both HPSE expression and activity decreased significantly in 17 patients following tumour resection, but increased markedly in six patients, coincident with recurrence or metastasis." (PMID 31327867, 2019). "This review describes how leukocyte-heparanase can be a double-edged sword in tumor progression; it can enhance tumor immune surveillance and tumor cell clearance, but also promote tumor survival and growth." (PMID 31110966, 2019). "Meanwhile, TEXs secreted by cells over-expressing heparanase altered the cell biology of both tumor cells and host cells." (PMID 31438991, 2019). "HPSE is a highly versatile protein affecting multiple events in tumor progression, including cell adhesion, invasion and angiogenesis." (PMID 31001480, 2019). "Within this group of compounds, inhibitors of heparanase with lower anticoagulant activity than heparin were selected as candidates for development as anti-tumor agents." (PMID 31362364, 2019). "Intriguingly, leukocyte-derived heparanase has been shown to either assist or impede tumor progression, depending on the setting." (PMID 31110966, 2019). "Heparanase enzyme was revealed to promote lymphangiogenesis and tumor invasion in PNETs, where this enzyme produced by both TAMs and cancer cells is important for tumor progression." (PMID 30925924, 2019). "Regardless, the selective pressure from these vaccines on tumor cells to downregulate heparanase expression would still be advantageous in blocking tumor progression." (PMID 31110966, 2019). "Together, these findings show that heparanase from the tumor cells, macrophages, and epithelial cells can promote tumorigenesis." (PMID 31110966, 2019). "Injecting heparanase-pulsed DCs into mice before administering B16 tumor cells was shown to protect animals from tumor growth." (PMID 31110966, 2019). "Heparanase overexpression has been documented across the majority of tumor types, including solid tumors and hematological tumors." (PMID 31110966, 2019). "Similar data were obtained in a pancreatic carcinoma model leading to the interpretation that Hpa2 functions as a tumor suppressor in these carcinomas in a heparanase and HS independent manner." (PMID 31850210, 2019). "It has also been proposed that reduced adhesion of tumor cells to the underlying ECM, as well as increased cell motility, is due to cleavage of cell surface HS by heparanase produced by the tumor cell itself." (PMID 32010611, 2019). "The catalytic activity of heparanase requires acidic pH and is maximal between pH 5.0 and 6.0, which is the pH of late endosomes or lysosomes as well as the pH of the tumour microenvironment." (PMID 30845788, 2019). "More recently, the role of leukocyte heparanase in tumor progression has been more closely examined, with the suggestion that it can be either pro- or anti-tumorigenic, depending on the setting." (PMID 31110966, 2019). "These two examples indicate that heparanase can be beneficial for combatting tumor growth, as well as detrimental; the latter being more commonly highlighted." (PMID 31850210, 2019). "The overexpression of heparanase has been detected in almost all cancer types, where it promotes metastasis, angiogenesis, and tumor proliferation." (PMID 31110966, 2019).
tumor (continued). "In another study using gene-modified mice that lacked heparanase in natural killer (NK) cells, it was demonstrated that endogenous NK cell heparanase was required for effective tumor NK cell invasion and immune-surveillance." (PMID 31850210, 2019). "The compounds suppress the migration and the invasion of tumor cells but the complex biological activity suggests that in addition to heparanase other proteins are targeted." (PMID 31362364, 2019). "The present study elucidated the molecular mechanisms involved in the activation of heparanase expression in circulating lymphocytes, which was mediated by heparan sulfate and syndecans that were secreted in exosomes by tumor cells." (PMID 30922347, 2019). "Among other tumour cell procoagulant molecules, the enzyme heparanase (HPSE) is gaining increasing attention." (PMID 31327867, 2019). "The abundant exosomes are recognized by receptors that facilitate heparanase internalization; once cells take up heparanase, the enzyme triggers specific biological functions involved in tumor development." (PMID 30922347, 2019). "Exosomes secreted by tumor cells, together with high levels of heparanase, not only alter the behavior of tumor cells but also promote alterations to nonneoplastic host cells." (PMID 30922347, 2019). "The expression of this enzyme is upregulated during tumor progression and enhanced heparanase expression or exposure of cells to exogenous heparanase stimulates exosome secretion." (PMID 31546622, 2019). "It was proposed that by increasing expression of heparanase in tumor-infiltrating lymphocytes, the tumor would have the ability to alter gene expression of many other neoplastic and non-neoplastic cells." (PMID 31110966, 2019). "The latent heparanase was located on the surface of these exosomes and was readily taken up by tumor cells and activated, giving it the ability to modify the tumor microenvironment and so facilitate disease progression." (PMID 31850210, 2019). "Heparanase is elevated in multiple types of cancer and promotes tumor invasion, angiogenesis, and metastasis." (PMID 31195728, 2019). "Our understanding of the relationship between heparanase and leukocytes during tumor progression remains limited." (PMID 31110966, 2019). "At μM concentrations the inhibitors suppress the migration and invasion of tumor cells across through a Matrigel membrane which is mediated by their anti-heparanase activity." (PMID 31362364, 2019). "We also discuss the potential of using heparanase in leukocyte therapies against tumors, and the effects of heparanase inhibitors on tumor progression and immunity." (PMID 31110966, 2019). "Heparanase inhibitors that prevent the release of heparan sulfate side chains have been tested in pre-clinical and clinical settings, and reduce tumor metastasis by maintaining ECM integrity and partially restoring vascular function." (PMID 31195728, 2019). "A number of cell types express heparanase including leukocytes, cells of the vasculature as well as tumor cells." (PMID 31110966, 2019). "Heparanase has also been well-characterized in cancer, where the overexpression of heparanase often contributes to tumor progression." (PMID 31110966, 2019). "This review covers our current knowledge of heparanase in immune regulation of tumor progression, as well as the potential applications and implications of exploiting or inhibiting heparanase in cancer therapy." (PMID 31110966, 2019). "Again, the source of heparanase in this example is unclear, but this study supports the idea that tumor cells can utilize heparanase from the tumor microenvironment with similar outcomes on tumor progression." (PMID 31110966, 2019). "It was found to inhibit multiple targets involved in tumor progression and metastasis, including heparanase, VEGF, FGF2, P-selectin, and stromal cell-derived factor-1α (SDF-1α)." (PMID 31013618, 2019).